STYXL1 (serine/threonine/tyrosine interacting like 1)
Description:
Catalytically inactive phosphatase. By binding to G3BP1, inhibits the formation of G3BP1-induced stress granules. Does not act by protecting the dephosphorylation of G3BP1 at 'Ser-149'. Inhibits PTPMT1 phosphatase activity. By inhibiting PTPMT1, positively regulates intrinsic apoptosis. May play a role in the formation of neurites during neuronal development.
Synonyms: DUSP24; MKSTYX; MK-STYX
Tractability: PROTAC: ubiquitination databases record sites on it.
Gene: Protein-coding gene on chromosome 7 (75,996,315 to 76,048,809, reverse strand). Ensembl gene ENSG00000127952.
Subcellular location: Mitochondrion matrix
Gene Ontology:
Molecular function: phosphatase inhibitor activity; protein binding; protein phosphatase binding; pseudophosphatase activity
Biological process: negative regulation of stress granule assembly; positive regulation of intrinsic apoptotic signaling pathway; positive regulation of neuron projection development; regulation of intrinsic apoptotic signaling pathway; intracellular signal transduction
Cellular component: mitochondrial matrix; mitochondrion
Genetic constraint (gnomAD): Loss-of-function variants: 29 observed, 32.51 expected, observed/expected ratio (o/e) 0.89, 90% interval 0.66 to 1.22. The upper end of that interval is the gene's LOEUF score, 1.22, which puts it in group 5 of 6, group 1 being the genes least tolerant of losing a copy. Missense variants: 343 observed, 393.64 expected, observed/expected ratio (o/e) 0.87, 90% interval 0.8 to 0.95. Synonymous variants: 125 observed, 146.05 expected, observed/expected ratio (o/e) 0.86, 90% interval 0.74 to 0.99.
Homologues: Orthologues: chimpanzee STYXL1 (98% identical), macaque STYXL1 (83% identical), guinea pig STYXL1 (75% identical), rabbit STYXL1 (71% identical), rat Styxl1 (66% identical), mouse Styxl1 (65% identical), pig STYXL1 (57% identical). Paralogues in human: DUSP8 (23% identical), DUSP2 (22% identical), DUSP9 (22% identical), DUSP6 (22% identical), DUSP1 (21% identical), DUSP10 (21% identical), DUSP16 (21% identical), DUSP7 (21% identical), SSH2 (21% identical), DUSP5 (21% identical), SSH3 (20% identical), SSH1 (20% identical), and 19 more.
Diseases named in the same sentence as STYXL1 in open-access papers:
STYXL1 is named in the same sentence as 18 diseases in open-access papers, as found by Europe PMC text mining. Sharing a sentence is not in itself a finding about the gene and the disease. The quoted sentences say what the papers report.
Ewing sarcoma (3 papers, 2010 to 2021). A small round cell tumor that lacks morphologic, immunohistochemical, and electron microscopic evidence of neuroectodermal differentiation. "EWS-FLI1 oncoprotein binds an ETS binding motif of STYXL1, greatly increasing the expression of MK-STYX, resulting in Ewing sarcoma, a pediatric bone cancer." (PMID 34203203, 2021). "Furthermore, the misregulation of MK-STYX (STYXL1) has been found in Ewing’s sarcomas (Figure (6Bi))." (PMID 34203203, 2021).
Intellectual disability (3 papers, 2016 to 2017). "Recently, a homozygous missense mutation in STYXL1 was identified in patients with moderate intellectual disability accompanied with seizures and behavioral complexities, and the expression level of STYXL1 mRNA in the EBV-transformed lymphoblastoid cells in those patients was decreased." (PMID 26926397, 2016). "STYXL1 has recently been suggested as a candidate gene involved in intellectual disability and seizures." (PMID 28902166, 2017).
diabetes (2 papers, 2022 to 2023). "Most genes have been related to diabetes and cancer, with most of them being linked to pancreatic cancer (CEACAM6, HDAC5, HPCAL1, PARVG, and STYXL1)." (PMID 36360783, 2022).
depression (1 paper, 2016). "Among them, the expression levels of CIDEC, RNASE1, SLC36A1, and STYXL1 mRNA were significantly changed depending on the state of depression in the RT-qPCR analysis, which was consistent with the results of the microarray analysis." (PMID 26926397, 2016).
glioblastoma (1 paper, 2022). The most malignant astrocytic tumor (WHO grade IV). "STYXL1 can be significantly upregulated in glioblastoma (GBM)." (PMID 36106167, 2022).
male infertility (1 paper, 2024). The inability of the male to effect fertilization of an ovum after a specified period of unprotected intercourse. "Deletion of Styxl1 led to male infertility and MMAF with defective axonemal microtubule arrangements." (PMID 38168070, 2024). "Taken together, Styxl1 deletion results in reduced sperm motility and increased morphological abnormalities of sperm accounting for male infertility." (PMID 38168070, 2024). "Deletion of Styxl1 results in male infertility and microtubule defects of sperm flagella." (PMID 38168070, 2024).
psoriasis (1 paper, 2024). An autoimmune condition characterized by red, well-delineated plaques with silvery scales that are usually on the extensor surfaces and scalp. "The most significant shared SNP for HDL and psoriasis was also rs184114817 (pCAPSSOC=2.58×10-8), and the gene within clumping area was STYXL1." (PMID 38550599, 2024).
cancer (4 papers, 2014 to 2022). A tumor composed of atypical neoplastic, often pleomorphic cells that invade other tissues. "In this carcinoma, STYXL1 (Serine/Threonine/Tyrosine Interacting Like 1) promotes malignant progression via the downregulation of CELF2 and the activation of the PI3K/Akt pathway." (PMID 34681716, 2021).
tumor (2 papers, 2018 to 2020). "DNAJC10, RNF149 and STYXL1 all harbored significantly higher mRNA expression levels in tumor tissues compared to normal prostate." (PMID 29890952, 2018). "c Flank xenograft final tumor weight after 5 weeks using lentiviral ectopic over-expression of candidate genes RNF149 and STYXL1 in the LNCaP PC cell line." (PMID 29890952, 2018). "b Flank xenograft tumor growth over time using lentiviral ectopic over-expression of candidate genes RNF149 and STYXL1 in the LNCaP PC cell line." (PMID 29890952, 2018). "None of the other genes DNAJC10, RNF149 or STYXL1 had a significant effect on tumor growth or tumor weight." (PMID 29890952, 2018).
STYXL1 also shares sentences with these, for which no sentence is quoted: neurodegenerative disease (2 papers); amyotrophic lateral sclerosis (1); bone cancer (1); epilepsy (1); hepatocellular carcinoma (1); male reproductive organ benign neoplasm (1); pancreatic cancer (1); pheochromocytoma (1); prostate adenocarcinoma (1).